CCL2 (C-C motif chemokine ligand 2)
Diseases named in the same sentence as CCL2 in open-access papers (continued):
Sharing a sentence is not in itself a finding about the gene and the disease.
infection (continued). "Surprisingly, we find that the presence of the interaction with E-cadherin does not affect the infection rate but modulates slightly the IL-6 release and in a more pronounced manner the CCL2 secretion." (PMID 23460827, 2013). "Mindful that the expression of chemokines and cytokines in the serum does not allow the localization of chemokine/cytokine producing cells, we used quantitative RT-PCR to determine the relative expression of Ifng, CXCL10, CCL2 and CLL7 in spleen versus BM during infection with P. chabaudi." (PMID 23762028, 2013). "Altogether, these results indicate that the increase in MCP-1/CCL2 and NO levels induced by the treatment of septic mice with rPAF-AH leads to a more efficient bacterial clearance at the site of infection and therefore impacts the beneficial effects of this enzyme in septic conditions." (PMID 24069320, 2013). "In the present study, transcript levels in rabbit lungs were measured at 3 hours post-infection, whereas protein and transcript levels of TNF-α and CCL-2 were determined at 7, 14, 21, 28 and 60 days in infected mice or 24, 48, 72 and 96 hours in Mtb-infected human PBMC, in other published reports." (PMID 23958185, 2013). "In addition, higher concentrations of mRNA for IFN-γ CCL2 and CCL5, as well as protein, but lower numbers of apoptotic cells, were found in lesions from TNFR1 KO mice than in WT, at late time points of infection." (PMID 22203861, 2012). "Furthermore, MVA infection induces pro-inflammatory cytokines such as TNF-α, type I interferons and chemokines like CCL2 that attract leucocytes to the site of inoculation." (PMID 22396645, 2012). "Elicited macrophages from both CD200R1+/+ and CD200R1−/− mice were infected with HSV-1 (multiplicity of infection; MOI = 10), or challenged with Pam2CSK4 (100 ng/ml), or LPS (100 ng/ml), and levels of IL-6, CCL5 (Rantes), or CCL2 (MCP-1) were measured at 24, 48, and 72 h." (PMID 23082204, 2012). "Mice lacking CCL2 or CCR2 exhibit diminished inflammatory monocyte recruitment to infection sites resulting in enhanced bacterial growth and overwhelming infection." (PMID 22629382, 2012). "Chemokine C-C motif ligand 2 (CCL2), also known as monocyte chemoattractant protein 1 (MCP-1), is a member of the chemokines family and can specifically recruit monocytes to sites of inflammation, infection, trauma, toxin exposure, and ischemia." (PMID 22721162, 2012). "CXCL2, CCL2 and IFN-λ levels were also decreased to varying degrees one day after infection." (PMID 21637773, 2011). "For example, genes encoding several innate immune receptors and chemokines (such as TLR4, CD83, CCL2, CXCR4, CXCL5, IL1A and IL8)—several of which participate in the initiation of a T cell response during infection —showed increased relative expression in the BTB animal group." (PMID 22182502, 2011). "After 48 h of infection, MVA-B induced higher production of IL-7, IL-15, MCP-1/CCL2 and MIG/CXCL9 than uninfected MDDC, indicating that some mediators are secreted at later times post-infection and/or at low doses possibly because is necessary some degree of maturation to up regulate such mediators." (PMID 21625608, 2011). "The duration of the infection period did not affect Ccl2 expression in sham-infected mice, and P. gingivalis infection consistently induced the up-regulation of gene expression." (PMID 21625524, 2011). "In addition, P3 infection suppressed the expression of interferon (IFN)-α and tumor necrosis factor (TNF)-α but enhanced the production of chemokine (C-C motif) ligand 2 (CCL2) and interleukin (IL)-10 of DCs." (PMID 21269456, 2011). "Infection with M. tuberculosis infection in these chimeras resulted in disorganized tuberculous granulomas in which CCL2 was consistently absent." (PMID 22114556, 2011). "This is not surprising as CCL-2 plays an important role in recruitment of T memory cells to the site infection which are long lived in a BCG vaccinated population." (PMID 21991356, 2011).
infection (continued). "MCP-1 (Monocyte chemotactic protein-1) is a small cytokine belonging to the CC chemokine family, also known as Chemokine (C-C motif) ligand 2 (CCL2), which recruits monocytes, memory T cells, and dendritic cells to sites of tissue injury and infection." (PMID 20356392, 2010). "CXCL1 and CCL2 expression after infection with UV-inactivated virus was not statistically different from that with intact virus." (PMID 20419141, 2010). "It is noteworthy that IL-10 levels were maintained close to the basal level among infected animals on the 7th and 21st days p.i., while pro-inflammatory cytokine levels (TNF-α, CCL2, IL-6 and IFN-γ) presented a great variation among different experimental groups during the acute phase of infection." (PMID 20967289, 2010). "A comparative study using Plasmodium berghei ANKA infected C57BL/6 and BALB/c mice indicated th at both strains of mice expressed CXCL10 (interferon-induced protein 10, IP-10) and CCL2 (monocyte chemotactic protein-1, MCP-1) chemokine genes as early as 24 hours post-infection." (PMID 16359553, 2005). "Indeed, the supernatant from lung homogenates revealed elevated IL-4, IL-12, and MCP-1 (CCL2) production 7 days post-infection with melanized C. neoformans compared to non-melanized cells in tandem with a higher fungal burden." (PMID 41378875, 2026). "BR15 infection induced a modest but statistically significant increase in TNF-α expression (p < 0.05) and a significantly higher expression of IFN-β1, IL-1β, IL-6, and IL-10, as well as the chemokines CCL2 (MCP-1), CCL5 (RANTES), and CXCL8 (IL-8), compared to MR766-infected cells." (PMID 40732762, 2025). "Additionally, severe influenza virus infection was associated with hypercytokinemia, including increased cytokine (IFNβ, TNF, IL-10 and IL-12p70) and chemokine (MCP-1 (CCL2), KC (CXCL1), IP-10 (CXCL10) and RANTES (CCL5)) levels in the severe infection group at 7 dpi." (PMID 41285788, 2025). "Macrophages migrate to the infection site via chemotaxis, where they recognize and phagocytize fungal pathogens while producing various pro-inflammatory cytokines and chemokines, including TNFα, CXCL1, CXCL2, CCL2, and IL-1β, thereby promoting inflammation and immune defense." (PMID 41190069, 2025). "Furthermore, the expression levels of leukocyte migration‐related cytokines (CCL2 and CCL8) were high in PE but very low in PB, which may be related to the need for cytokines to migrate to the site of infection (pleura)." (PMID 40170555, 2025). "Infections with pso variants (especially with the HK2 variant lacking O-Ag biosynthesis) activated endothelial cells with abundant expression of cell adhesion molecules (ICAM-1 and VCAM-1) and inflammatory mediators (CCL2, CXCL1, CXCL8, CCL20, and IL-6)." (PMID 40570043, 2025). "As both WNV and USUV-infected in vitro BBBs showed comparable measures of barrier function to mock, the reduction in MMP-9 and CCL2 concentrations was therefore not sufficient to induce a direct, detectable decrease in permeability of the barrier as a response to infection." (PMID 40295794, 2024). "Additionally, we found that CCL2 was highly expressed in the in vitro BBB, with concentrations in mock peaking at 4.43 x 104 pg/ml at 72 hpi, but infection with USUV (p = 0.0368) and WNV (p < 0.0001) resulted in a significantly lower concentration at 24 hpi compared to mock." (PMID 40295794, 2024). "Consistent with higher Ccl2 expression in WT mice at 12 and 16 hours after infection, the percentage and total number of inflammatory Ly6Chi monocytes (CD45+CD11c–CD11b+Ly6ChiLy6G–) in the dLN was significantly greater in WT mice at 12 and 16 hours after infection compared with MARCO–/– mice." (PMID 38194268, 2024). "Moreover, CCL2, CCL21, CXCL2, CXCR2, and CXCR3 mRNAs were significantly induced at 6–12 h after V. harveyi infection, implying that P. leopardus immune cells can be activated and recruited to the sites of infection at early time points post-infection." (PMID 39450165, 2024).
infection (continued). "By infecting mice specifically deficient in astrocyte CCL2 production (GFAP-Cre x CCL2fl/fl), we observed significantly decreased immune cell recruitment to the brain and reduced parasite control during chronic, but not acute, infection." (PMID 38206985, 2024). "Moreover, CCL2/7 were significantly increased after infection with Fn but not with B. fragilis control." (PMID 36693067, 2023). "Monocyte chemoattractant protein 1 (MCP1), also commonly referred to as chemokine ligand 2 (CCL2), exerts an important role in regulating the inflammatory response by enhancing the recruitment of monocytes, memory T cells, and dendritic cells to the sites of injury or infection." (PMID 36860846, 2023). "Cytokine signaling of IL-1β, IL-23, IL-17A, CCL7, CXCL10, TRAIL, CD40L, and BAFF provides protection against acute WNV infection in mice; IL-10 and IL-22 aid in WNV pathogenicity; IL-6 and IL-12 had no apparent effect during infection; and CCL2, TNF-α, and FasL roles remain elusive." (PMID 36992514, 2023). "Interestingly, in blood, elevated plasma levels of CCL2 correlated positively with IM frequencies (R=0.639, p=0.048), which were significantly elevated in IAV patients, indicating a role for CCL2 in the changes to the IMs during infection." (PMID 36752598, 2023). "We include it for context since extensive prior work has used it to model epithelial cell infection and found that it produces a cytokine repertoire partially overlapping other cell lines, as well as CCL2 (MCP-1), which is not characteristic of epithelial cells." (PMID 37068092, 2023). "We then further investigated whether TFRC affected STAT3 expression in cardiomyocytes, and found that overexpression of TFRC in cardiomyocytes by AAV9‐flag‐TFRC infection significantly increased STAT3 and phosphroylated STAT3 (p‐STAT3) expression, and Ccl2 mRNA expression." (PMID 37647427, 2023). "However, CCL2KO did not affect infection of macrophage in mice suggesting that the cellular and soluble factor environment for EcoHIV infection in vivo is less dependent upon CCL2 than in macrophage culture." (PMID 37085605, 2023). "However, NCI observed here after IC infection of CCL2KO mice manifests in the absence of a functional CCL2 gene." (PMID 37085605, 2023). "However, comparisons between vaccinated mice showed that H7N7 infection did not significantly increase levels of CCL2 (p = 0.94), IFNγ (p = 0.97), IL1β (p = 0.52), and IL-6 (p = 0.59) in the lungs compared to vaccinated mice receiving PBS." (PMID 37063291, 2023). "In fact, a previous study demonstrated a higher transcriptional level of the chemokine genes (CCL2 and CCL20) after infection of THP-1 cells with V. vulnificus, confirming that monocytes played an equally important role as other immune-related cells to control the infection process." (PMID 35874671, 2022). "Interestingly, while SIV infection significantly increased CXCL10 and CXCL11 in the hippocampus, it did not increase CCL2 in this area, suggesting regionally specific responses to infection." (PMID 35494221, 2022). "Similarly to CCL2/MCP-1, it attracts leukocytes to the focus of infection." (PMID 36012323, 2022). "Concomitantly to autophagy activation in MERS-CoV-MA-Δ4b infection, a significant decrease in the pro-inflammatory response was observed in MRC5 cells, including the expression of IFN-ß, NF-kB dependent cytokines (IL-6 and IL-8) and chemokines (CCL2 and CXCL10)." (PMID 36129908, 2022). "Among the selected cytokines or chemokines, IL-6, GM-CSF, CXCL1, CCL2, MIP-1α, MIP-2, IFN-α, and M-CSF (which are involved in acute inflammation and B cell maturation) were highly upregulated, although they exhibited transient inhibition at 1 day post-infection." (PMID 34068322, 2021). "At 5–7 d.p.i., increased expression of CCL2 mRNA in δWD mice was coincident with extensive macrophage/monocyte infiltration into lung parenchyma observed by IH which was not seen in controls or the lungs of δWD mice before infection with virus (EV2)." (PMID 33586810, 2021).
infection (continued). "Analyses of the cytokine production (MCP-1 and TNF), macrophage infiltration (estimated by Adgre1 (F4/80) expression), and Nos2 (iNOS) induction in the infected lungs detected a higher expression of Ccl2 (MCP-1), Adgre1, and Nos2 in Trem2−/− mice than in WT mice at day 3 after infection." (PMID 33863908, 2021). "Furthermore, in single-cycle infectivity tests using TZMbl cells, we did not see any effect of CCL2 depletion on the establishment of infection." (PMID 31172941, 2019). "Also, the changes on levels of chemokines can be related to the resistance to infection by Leptospira, but it was independent of CCL2 treatment." (PMID 30616505, 2019). "Therefore, IL-1β, CCL2, and CCL3 may be useful biomarkers for tracking infection and determining when antibiotic treatment could be terminated as well as for diagnosis, although additional studies are needed to validate this possibility." (PMID 31262978, 2019). "The activation of NF-κB and expression of TNF-α at the infection site in C. albicans-infected fish, combined with the qPCR data showing that the chemokines CXCL8 and CCL2 were upregulated only in C. albicans infection, suggested that phagocytes might be recruited only to C. albicans infections." (PMID 31088918, 2019). "All together, these human and murine data provide robust evidence for a non-redundant role of CCL2 in myeloid cell priming toward infection through the use of CCL2-blocking antibodies, CCL2 knockout mice, and transgenic mice in in vitro and in vivo experiments." (PMID 31921102, 2019). "CCL2 is readily produced by muscle cells in response to damage, inflammation or infection and potently recruits monocytes and macrophages upon engagement of the highly expressed CCR2 receptor, concomitantly setting up an autocrine amplification of the CCL2 chemokine in the monocytes and macrophages." (PMID 31084714, 2019). "This differential expression extended to the protein level as CCL2 was expressed at the highest level in SVEC4-10 cells treated with EVs isolated 14 days post-Mtb infection with minimal expression above controls when using serum EVs from day 7 and 21 post-infection." (PMID 29851993, 2018). "At the molecular level, the diminished recruitment of inflammatory monocytes seen in the Δnrp strain may be explained by a lower expression of CCL2 and CCL7, chemokines that play a role in the recruitment of myeloid cells to the site of infection, in the lungs of these animals." (PMID 30381350, 2018). "Monocyte recruitment depends on the infection of resident macrophages and requires recognition of bacterial phenolic glycolipids, cytosolic sensing via stimulator of interferon genes (STING), and expression of C-C motif chemokine ligand 2 (Ccl2), a potent monocyte chemoattractant." (PMID 29173800, 2018). "Furthermore, the accumulation of IMs, but not AMs, in the infected lung is impaired in the absence of CCL2, a chemokine that is responsible for mobilization/recruitment of monocytes to the blood and lung during infection." (PMID 29500179, 2018). "At 2–6 h post infection, S. epidermidis nosocomial strain 1457 was demonstrated to induce a rapid production of cytokines, such as TNF-α, IL-1β, IL-6, IL-12p70 and IL-10, as well as chemoattractant protein-1 (MCP-1), granulocyte-colony stimulating factor (G-CSF), CCL2 and CXCL1." (PMID 29405832, 2018). "Similarly, CCL2 was significantly upregulated beginning at 1 DPI in mouse BALF and serum, and remained high in BALF up to 9 DPI; indeed, it remained high in mouse serum following Hb01 infection." (PMID 28421067, 2017). "We demonstrate that aprepitant treatment attenuates B. burgdorferi-induced elevations in CCL2, CXCL13, IL-17A, and IL-6 gene expression in dorsal root ganglia, spinal cord, and/or cerebrospinal fluid of rhesus macaques at 2 to 4 weeks following intrathecal infection." (PMID 28202084, 2017).
infection (continued). "In humans, following H7N9 infection, there is excessive expression of pro-inflammatory factors CCL2, IL-6, IL-8, IFNα, interferon-γ, IP-10, MIG and macrophage inflammatory protein-1β, which has been shown to contribute to fatal disease outcomes in mouse models of infection." (PMID 28435679, 2017). "Furthermore, the MCPs including CCL2, CCL7, CCL8, and CCL12, which were evaluated in a few studies, might be useful biomarkers to distinguish the infection stages of this disease." (PMID 28752079, 2017). "Obviously, some cells can respond to virions and virus constituents via mechanisms that do not require active infection, such as pathogen (or pattern) recognition receptors, but our findings indicate that inoculation with UV-inactivated virus did not elicit CCL2 production in the brain at 3 hpi." (PMID 29202854, 2017). "We further examined the gene expression of pro-inflammatory chemokines (CXCL1, CXCL2 and CCL2), chemokine receptor CCR7, and TLR4 in lung tissues in order to determine the potential mechanism(s) of immune cells infiltration into the lungs of newborns following low dose infection with B. pertussis." (PMID 28798335, 2017). "Consistent with previous reports, histopathological evaluation of archived lung tissues from CCL2 Tg and WT mice showed that 50 % of CCL2 Tg mice developed OP after infection with S. pneumoniae, while control mice did not respond with OP after infection with S. pneumoniae." (PMID 27282780, 2016). "Indeed, CCL2−/− mice were unable to contain the virus and failed to recruit inflammatory monocytes to the infection site." (PMID 25918478, 2015). "Specific chemokines, such as IP-10, IL-8, MIG/CXCL9 and MCP-1/CCL2 are released from monocytes, alveolar macrophages and polymorphonuclear granulocytes to recruit NK cells, γδ T lymphocytes, and αβ T lymphocytes of CD4+ and CD8+ phenotypes in sequential order into the site of MTb infection." (PMID 25135111, 2014). "However, at day 3 post-infection, the Socs4R108X/R108X mice showed significantly higher levels of cytokines and chemokines, such as IL-1β, IL-4, IL-5, IL-6, IL-12p40, IL-13, IFN-γ, and KC (CXCL1), MIP-2 (CXCL2) and MCP-1 (CCL2), respectively." (PMID 24809749, 2014). "Although MIF can induce CCL2 and trigger monocyte recruitment and subsequent arrest in tissue, the bone marrow emigration and recruitment of inflammatory monocytes in tissues during the acute stage of infection was found independent of MIF." (PMID 25255103, 2014). "However, at 11 weeks of infection, when lesions were significantly different, we found higher expression of CCL5 and CCL2 mRNA and, at 20 weeks afterinfection, we found higher concentrations of CCL5 and CCL2 protein in lesions." (PMID 22203861, 2012). "It should be noted that ISGs with antiviral activity in control cells might not appear as antiviral in ZAP cells due to infection rates being near the 85% cutoff (e.g. CCL2), or due to a failure to meet our analysis criteria in ZAP cells (e.g. RPL22)." (PMID 22615998, 2012). "Infections of N-PRRSV viruses resulted in fever and inflammatory response, as indicated by high expression of proinflammatory cytokines and chemokines, adhesion molecules, inflammatory enzymes and receptors, such as IL-1β, IL8, SELL, ICAM, CCL2, CXCL9, CXCL10, B2M, proteasomes, cathepsins." (PMID 20614006, 2010). "infection and present in the CM Ba, CM Bs, and CM Bm, might be involved in wound closure inhibition, we preincubated CM from infected cells and CM NI for 1 h with two concentrations of neutralizing antibodies against CXCL8 and CCL2 (0.5 and 1 μg/mL) before repeating the wound healing assay." (PMID 40943115, 2025). "Acute HIV infection also induces production of chemokines (CCL2, CCL3, CCL4, and CCL5), which may recruit uninfected monocytes/macrophages and/or CD4+ T lymphocytes to the sites of virus replication, thus promoting the spread of infection and/or the establishment of virus reservoirs." (PMID 40507836, 2025).